ECE1 (endothelin converting enzyme 1)
Description:
Converts big endothelin-1 to endothelin-1.
Synonyms: ECE
Tractability: Small molecule: a drug acting on it is in phase 2 or 3 trials; a structure with a bound ligand is known; a high-quality ligand is known; it has a high-quality binding pocket; it belongs to a druggable protein family. Antibody: UniProt places it where antibodies can reach, with high confidence; its Gene Ontology location is reachable by antibodies, with high confidence; UniProt predicts a signal peptide or a membrane-spanning region. PROTAC: ubiquitination databases record sites on it; its protein half-life has been measured; a small molecule that binds it is known.
Target class: Metallo protease; Enzyme; Metallo protease MAE clan; Metallo protease M13 family; Protease
Chemical probes: CHEMBL191879, LY-292223
Gene: Protein-coding gene on chromosome 1 (21,217,247 to 21,345,572, reverse strand). Ensembl gene ENSG00000117298.
Subcellular location: Cell membrane
Pathways (Reactome):
Signal Transduction: Peptide ligand-binding receptors
Gene Ontology:
Molecular function: endopeptidase activity; metalloendopeptidase activity; protein binding; protein homodimerization activity; zinc ion binding; peptide hormone binding; metallopeptidase activity
Biological process: bradykinin catabolic process; calcitonin catabolic process; ear development; embryonic digit morphogenesis; endothelin maturation; heart development; hormone catabolic process; peptide hormone processing; positive regulation of receptor recycling; protein processing; substance P catabolic process; G protein-coupled receptor signaling pathway; regulation of systemic arterial blood pressure by endothelin; regulation of vasoconstriction; anatomical structure morphogenesis; axon guidance; axonogenesis involved in innervation; embryonic heart tube development; gene expression; neuron projection development; proteolysis; semaphorin-plexin signaling pathway; signal transduction; sympathetic neuron axon guidance
Cellular component: endosome; external side of plasma membrane; extracellular exosome; lysosomal membrane; membrane; perinuclear region of cytoplasm; plasma membrane; Weibel-Palade body; endosome membrane; vesicle
Genetic constraint (gnomAD): Loss-of-function variants: 35 observed, 96.22 expected, observed/expected ratio (o/e) 0.36, 90% interval 0.28 to 0.48. The upper end of that interval is the gene's LOEUF score, 0.48, which puts it in group 2 of 6, group 1 being the genes least tolerant of losing a copy. Missense variants: 814 observed, 1,033.1 expected, observed/expected ratio (o/e) 0.79, 90% interval 0.74 to 0.83. Synonymous variants: 394 observed, 407.43 expected, observed/expected ratio (o/e) 0.97, 90% interval 0.89 to 1.05.
Homologues: Orthologues: chimpanzee ECE1 (99% identical), macaque ECE1 (97% identical), guinea pig ECE1 (96% identical), rat Ece1 (95% identical), dog ECE1 (94% identical), mouse Ece1 (94% identical), pig ECE1 (93% identical), rabbit ECE1 (86% identical), tropical clawed frog ece1 (78% identical), zebrafish ece1 (66% identical), Drosophila melanogaster Nep3 (44% identical), Drosophila melanogaster Nep4 (38% identical), and 20 more. Paralogues in human: ECE2 (62% identical), MME (37% identical), MMEL1 (37% identical), ECEL1 (37% identical), PHEX (34% identical), KEL (29% identical).
Diseases named in the same sentence as ECE1 in open-access papers:
ECE1 is named in the same sentence as 75 diseases in open-access papers, as found by Europe PMC text mining. Sharing a sentence is not in itself a finding about the gene and the disease. The quoted sentences say what the papers report.
Hypertension (11 papers, 2010 to 2025). The presence of chronic increased pressure in the systemic arterial system. "The polymorphisms in the ECE1 gene have been implicated in human essential hypertension, whereas ABHD16A is shown to be associated with coronary artery aneurism." (PMID 34996843, 2022). "Candidates EDNRA, EDN1 and EDNRB function together in a regulatory pathway with endothelin-converting enzyme ECE1, which has been implicated in essential hypertension." (PMID 20886000, 2010). "Likewise, the ECE1 C-338A polymorphism is strongly associated with hypertension." (PMID 33919522, 2021). "Of these genes, A2ML1, AGGF1, CBS, ECE1, GABRB3, GALNT2, MRPS6/SLC5A3, and SPG7 had documented associations with hypertension, ischemic stroke and methionine metabolism, atherosclerosis, and early-onset MI." (PMID 34252155, 2021). "The risk allele of the ECE1 C-338A polymorphism interferes with E2F2 binding and endothelial ECE-1b expression and facilitates hypertension." (PMID 33919522, 2021). "In addition, previous studies have found an increase in ECE1 in pathological conditions, for instance, hypertension, coronary atherosclerosis, and vascular injury models." (PMID 38980841, 2024). "The ECE1 gene polymorphisms have been studied as a candidate gene in essential hypertension, but no consensus has been reached." (PMID 32107880, 2020). "Furthermore, inhibition of ECE-1 attenuated atherosclerosis and hypertension." (PMID 31231580, 2019).
candidiasis (7 papers, 2008 to 2024). Infection with the organism Candida. "By using a similar approach to thatfollowed to study the diagnostic potential of the Hyr1, the ECE1 gene has been expressed in E. coli and used in both immunoblottingand ELISA assays to detect antibodies in patients with invasive candidiasis." (PMID 18382617, 2008). "Our cell-based studies are also in accordance with in vivo mouse and zebrafish candidiasis models that link ECE1 expression with C. albicans pathogenicity and invasiveness." (PMID 34986345, 2022). "ALS3 and RBT1 deletion mutants have no role or a reduced effect, respectively, on the virulence of C. albicans in BALB/c mice in a systemic model of candidiasis; presently there are no reports describing an ECE1 murine virulence study." (PMID 24260489, 2013).
Alzheimer disease (5 papers, 2014 to 2024). A progressive, neurodegenerative disease characterized by loss of function and death of nerve cells in several areas of the brain leading to loss of cognitive function such as memory and language. "In human studies, Western individuals homozygous for the C-338A polymorphism (AA) within the ECE1 gene promoter region have been shown to be at reduced risk of developing late-onset Alzheimer’s disease (LOAD)." (PMID 39456746, 2024). "To date, these investigations have comprised in vitro or in vivo rodent studies It is not yet clear whether enhancing ECE-1 activity is a potential drug target in Alzheimer's disease rather than inhibiting ECE-1, as in the periphery." (PMID 25131455, 2014).
glioblastoma (5 papers, 2008 to 2025). The most malignant astrocytic tumor (WHO grade IV). "circNDC80 has been found as an oncogenic factor in the development of glioblastoma through the miR-139-5p/ Endothelin-converting enzyme-1 (ECE1) pathway that preserves the stemness of GSCs to enhance GSC self-renewal." (PMID 39877636, 2025). "According to our research, circNDC80 is an oncogenic factor that promotes glioblastoma through the miR-139-5p/ECE1 pathway." (PMID 36635757, 2023). "Studies have shown that a series of thiol ECE1 (endothelin converting enzyme 1) inhibitors exert rapid inhibitory effects on human glioblastoma cells." (PMID 36635757, 2023). "This analysis showed that ECE1 mRNA levels were increased in glioblastoma (GBM) tumors compared to lower-grade gliomas, including oligodendroglioma, oligoastrocytoma, and astrocytoma." (PMID 36766848, 2023).
prostate carcinoma (5 papers, 2004 to 2023). A carcinoma that arises from epithelial cells of the prostate gland. "In this study we present analysis of the post-transcriptional regulation of ECE-1 and its implications in prostate cancer." (PMID 24497914, 2014). "Elevated levels of ECE-1 have been observed in a range of malignancies, with high expression conferring poor prognosis and aiding the acquisition of androgen independence in prostate cancer." (PMID 24497914, 2014). "ECE-1 is upregulated in a number of cancers, including prostate cancer, leading to increased levels of ET-1 peptide." (PMID 24497914, 2014). "Abolition of the ECE-1 APA sites reduced protein expression from a reporter vector in prostate cancer cells, suggesting these sites are functional." (PMID 24497914, 2014). "Our study reveals that alterations in the balance of two membrane-bound metallopeptidases, NEP and ECE-1, can produce stroma that modulates the invasive potential of prostate cancer epithelial cells." (PMID 15083188, 2004). "The current study concludes that downregulation of NEP in prostate cancer epithelial cells allows mitogenic peptides to impart growth signals to the developing tumour, while in the surrounding prostate stroma elevated ECE-1 provides a local source of active ET-1 which encourages invasion." (PMID 15083188, 2004). "ECE1 silencing or overexpression have been described to decrease or increase phosphorylation (i.e., activation), respectively, of focal adhesion kinase (FAK) in prostate cancer cells." (PMID 32850305, 2020). "However, exogenous ET1 does not rescue the negative effects of ECE1 silencing on the invasiveness of prostate cancer cells, suggesting an effect that is independent of ET1 production." (PMID 36766848, 2023).
diabetes (4 papers, 2013 to 2025). "Interestingly, one such impaired enzyme system in diabetes-induced murine models were amyloid-beta degrading enzymes, namely, endothelin-converting enzyme 1 (ECE-1) and insulin-degrading enzyme (IDE)." (PMID 38255204, 2024). "PKC, activated in diabetes, is a known mediator of ECE-1 activation." (PMID 24350240, 2013). "In addition, endothelin-converting enzyme (ECE)-1, which catalyzes the conversion of the prohormone to the active compound ET-1, is also upregulated in diabetes." (PMID 24350240, 2013). "Furthermore, ECE-1 is likely a HIF-target gene, and possibly enhanced medullary ECE-1 is triggered by HIF, induced by both diabetes and contrast media." (PMID 24350240, 2013). "Given these mechanistic links and the known role of ET-1 in other vasculopathic models, we hypothesized that HFD-induced dyslipidemia may activate the ECE-1/ET-1 axis in the retina, contributing to early microvascular dysfunction even in the absence of overt diabetes." (PMID 40951441, 2025).
Hirschsprung disease (4 papers, 2013 to 2023). Hirschsprung disease (HSCR) is a congenital intestinal motility disorder that is characterized by signs of intestinal obstruction due to the presence of an aganglionic segment of variable extent in the terminal part of the colon. "ECE1 has been implicated in Hirschsprung disease, autonomic dysfunction, and cardiac defects." (PMID 36369750, 2023). "In addition, loss-of-function mutations in ECE1 are associated with Hirschsprung's disease." (PMID 36619519, 2022).
vaginal candidiasis (4 papers, 2017 to 2021). "Although the ece1 mutant strains can still form hyphae and invade the host epithelium, studies have shown that these mutants fail to cause epithelial cell damage and activate pro-inflammatory signaling (danger) pathways in oropharyngeal and vulvovaginal candidiasis." (PMID 30841504, 2019). "In summary, this study demonstrates that genetic variation at the ECE1 locus contributes to reduced pathogenicity of C. albicans clinical isolate 529L during vulvovaginal candidiasis." (PMID 34506615, 2021). "Our previous studies have shown that two key hyphae-associated genes, ECE1 and HWP1, were overexpressed during human vaginal candidiasis, and that their upregulation was associated with NLRP3 inflammasome activation, a crucial player in the immunopathogenesis of VVC." (PMID 34946178, 2021).
autonomic dysfunction (3 papers, 2014 to 2023). "Ece1 is known to regulate proteolysis of endothelin precursors into biologically active peptides, and loss of function is associated with cardiac defects, generalized edema, and autonomic dysfunction." (PMID 33284134, 2021).
colon carcinoma (3 papers, 2015 to 2024). "ECE1 activates multiple pathways related to cell proliferation, survival, and invasion, as demonstrated in the studies associated with colon cancer stem cells." (PMID 39691475, 2024). "They showed that in colon carcinoma and normal colon epithelial cells, PPET-1 and ECE-1 were found mainly in epithelial and endothelial cells, whereas ETAR was found in smooth muscle cells and in cancer associated fibroblasts." (PMID 37835445, 2023). "Inhibition also led to diminished protein levels of both endogen ECE-1 or GFP-fused N-terminal end of ECE-1c in 293T embryonic and DLD-1 colon cancer cells, which highlighted the importance of this motif on UPS-dependent ECE-1c degradation." (PMID 26543229, 2015).
glioma (3 papers, 2023 to 2024). A benign or malignant brain and spinal cord tumor that arises from glial cells (astrocytes, oligodendrocytes, ependymal cells). "High endothelin-converting enzyme 1 expression has been associated with glioma development because this enzyme increases tumor cell migration and invasion." (PMID 39063232, 2024). "Endothelin-converting enzyme 1 increases glioma cell migration and invasion; hence, it is a potential anti-glioma therapeutic target." (PMID 39063232, 2024). "Analysis of the CGGA data indicated that as the glioma grade increased, the expression of ECE1 also increased." (PMID 36635757, 2023). "This enzyme increases tumor cell migration and invasion, and it has been suggested that endothelin-converting enzyme 1 could be a novel marker for poor prognosis as well as a new anti-glioma therapeutic target." (PMID 39063232, 2024). "Thus, we assumed that miR-139-5p binds to the 3′ -UTRs of ECE1 to control the development of gliomas." (PMID 36635757, 2023).
ovarian carcinoma (3 papers, 2011 to 2025). A malignant neoplasm originating from the surface ovarian epithelium. "Consistent with our results, silencing of ECE1 in ovarian cancer cells has been shown to decrease ET‐1 production, MMP‐2 activity, and invasiveness." (PMID 31788944, 2020). "Furthermore, the topmost ranked genes in CR doublets included PRSS1, ECE1 and UBE2C, which promote ovarian cancer chemoresistance and progression." (PMID 40280979, 2025).
pulmonary hypertension (3 papers, 2014 to 2018). Increased pressure within the pulmonary circulation due to lung or heart disorder. "In this study, PETN therapy downregulated ET-1, ECE-1, and ET-1a/b receptor mRNA expression in MCT-induced pulmonary hypertension." (PMID 28337251, 2017). "Further, several important regulators of systemic/pulmonary hypertension including ADRA1D, ECE1, and EDNRA were upregulated in HAPE." (PMID 24465776, 2014).
vaginal infection (3 papers, 2019 to 2022). "Although differences in the levels of ECE1 gene expression between Candida species have been reported during vaginal infection in vitro and in vivo, it was unknown whether the C. dubliniensis and C. tropicalisECE1 genes also encode candidalysin peptide toxins and whether these are functional." (PMID 35073742, 2022). "As candidalysin drives neutrophil recruitment and immunopathology at the vaginal mucosa, ECE1 gene expression levels of both strains were measured by qRT-PCR during growth in RPMI-1640 and during murine vaginal infection." (PMID 34506615, 2021). "Furthermore, similar analyses demonstrate that C. dubliniensis and C. tropicalis express far less ECE1 than C. albicans when cultured on vaginal epithelial cells in vitro, and no ECE1 expression was observed in vivo in a murine vaginitis infection model." (PMID 35073742, 2022).
amyloid (2 papers, 2022 to 2023). "Indeed, PKCε has been associated with the activation of endothelin converting enzyme 1 (ECE-1), one of the main enzymes involved in amyloid β degradation and amyloid plaque reduction, rendering PKCε activation and overexpression as effective methods to reduce amyloid pathology." (PMID 37507998, 2023).
cardiomyopathy (2 papers, 2014 to 2022). A disease of the heart muscle or myocardium proper. "Endothelin-converting enzyme-1 ablation attenuated Dox-induced cardiomyopathy by preventing impaired mitochondrial biogenesis." (PMID 36557990, 2022).
dyslipidemia (2 papers, 2017 to 2025). "Our findings provide compelling evidence that HFD-induced dyslipidemia is associated with retinal inflammation and endothelial dysfunction, with ECE-1 and ET-1 serving as key mediators." (PMID 40951441, 2025). "Our findings support the association between systemic dyslipidemia—particularly elevated TC—and retinal endothelial dysfunction and inflammation, potentially involving the ECE‐1/ET‐1 axis." (PMID 40951441, 2025). "Our study provides compelling evidence that HFD‐induced dyslipidemia is intimately connected to retinal inflammation and endothelial dysfunction, mediated in part by the ECE‐1/ET‐1 axis." (PMID 40951441, 2025). "By shedding light on the ECE‐1/ET‐1 axis as a key molecular conduit between systemic dyslipidemia and retinal vascular pathology, we propose a new framework for understanding and potentially mitigating the ocular consequences of metabolic syndrome and related conditions." (PMID 40951441, 2025). "Mechanistically, dyslipidemia may induce oxidative stress and endothelial dysfunction, which in turn upregulate ECE‐1 transcription and ET‐1 production." (PMID 40951441, 2025).
endothelial dysfunction (2 papers, 2016 to 2025). In vascular diseases, endothelial dysfunction is a systemic pathological state of the endothelium (the inner lining of blood vessels) and can be broadly defined as an imbalance between vasodilating and vasoconstricting substances produced by (or acting on) the endothelium. "In addition, we observed marked upregulation of ECE‐1 and ET‐1, key mediators involved in vasoconstriction and endothelial dysfunction." (PMID 40951441, 2025). "Two of these proteins may be markers of endothelial dysfunction, such as von Willebrand Factor and endothelin converting enzyme 1 (not shown)." (PMID 27165192, 2016).
fungal infection (2 papers, 2019 to 2024). "Further, ece1 mutants were avirulent in the animal model of mucosal infection as well as zebrafish and murine models of systemic fungal infections." (PMID 31731583, 2019). "It has been hypothesized that ECE1/candidalysin-mediated cytolysis may be necessary for nutrient acquisition from host cells during fungal infection." (PMID 38427950, 2024).
HCMV infection (2 papers, 2021). "At an MOI of 10, HCMV infection completely abolished detectable levels of ECE-1 protein expression." (PMID 34070407, 2021). "To further examine if HCMV induces accumulation of ET-1 precursor protein via an effect on ECE-1 (the enzyme responsible for cleaving the preproET-1 into its mature active form ET-1), we examined if HCMV infection affected expression levels of the ECE-1 protein in HCMV-infected HUVECs." (PMID 34070407, 2021). "In support of this hypothesis, we recently found that HCMV infection inhibits ET-1 transcript expression, and via downregulation of endothelin converting enzyme-1 (ECE-1) that cleaves the ET-1 precursor protein to mature ET-1, it also inhibits release of the ET-1 peptide." (PMID 34831300, 2021).
Hyperglycemia (2 papers, 2020 to 2023). An increased concentration of glucose in the blood. "The expression of ET-1, a potent vasoconstrictor, was enhanced under hyperglycemia via the activation of endothelin converting enzyme-1 (ECE-1) in human umbilical vein endothelial cells (HUVECs), partly due to the activation of PKCδ." (PMID 37974282, 2023). "Anthocyanin-rich sour cherry extract was able to significantly reduce the hyperglycemia-induced enhanced gene expression of ET-1 and ECE-1." (PMID 33147748, 2020). "Further, although increased ET-1 and ECE-1 expression due to hyperglycemia was reduced by anthocyanin-rich sour cherry extract, NOS expression was increased by the extract." (PMID 33147748, 2020).